SLC25A26 (solute carrier family 25 member 26)
Description:
Mitochondrial S-adenosyl-L-methionine/S-adenosyl-L-homocysteine antiporter. Mediates the exchange of cytosolic S-adenosyl-L-methionine, the predominant methyl-group donor for macromolecule methylation processes, for mitochondrial S-adenosylhomocysteine(SAH), a by-product of methylation reactions.
Synonyms: SAMC; COXPD28
Tractability: Antibody: UniProt predicts a signal peptide or a membrane-spanning region. PROTAC: ubiquitination databases record sites on it.
Gene: Protein-coding gene on chromosome 3 (66,133,610 to 66,388,116, forward strand). Ensembl gene ENSG00000144741.
Subcellular location: Mitochondrion inner membrane
Subcellular location (Human Protein Atlas): Mitochondria
Pathways (Reactome):
Transport of small molecules: SLC-mediated transport of organic cations
Gene Ontology:
Molecular function: S-adenosyl-L-methionine transmembrane transporter activity; S-adenosyl-L-methionine:S-adenosyl-L-homocysteine antiporter activity
Biological process: macromolecule methylation; mitochondrial S-adenosyl-L-methionine transmembrane transport; S-adenosyl-L-methionine transport; amine transport; L-alpha-amino acid transmembrane transport; purine nucleoside transmembrane transport
Cellular component: mitochondrial inner membrane; mitochondrion
Genetic constraint (gnomAD): Loss-of-function variants: 8 observed, 13.01 expected, observed/expected ratio (o/e) 0.61, 90% interval 0.36 to 1.11. The upper end of that interval is the gene's LOEUF score, 1.11, which puts it in group 4 of 6, group 1 being the genes least tolerant of losing a copy. Missense variants: 216 observed, 172.7 expected, observed/expected ratio (o/e) 1.25, 90% interval 1.12 to 1.4. Synonymous variants: 73 observed, 68.75 expected, observed/expected ratio (o/e) 1.06, 90% interval 0.88 to 1.29.
Gene-disease validity (ClinGen):
ClinGen rates the evidence that SLC25A26 causes each of these diseases.
mitochondrial disease (autosomal recessive): Definitive.
Homologues: Orthologues: chimpanzee SLC25A26 (98% identical), rabbit SLC25A26 (91% identical), pig SLC25A26 (91% identical), rat Slc25a26 (88% identical), mouse Slc25a26 (88% identical), macaque SLC25A26 (83% identical), guinea pig SLC25A26 (82% identical), dog SLC25A26 (76% identical), zebrafish slc25a26 (68% identical), tropical clawed frog slc25a26 (63% identical), Drosophila melanogaster CG4743 (51% identical), Caenorhabditis elegans slc-25A26 (45% identical). Paralogues in human: SLC25A18 (31% identical), SLC25A22 (30% identical), SLC25A12 (26% identical), SLC25A13 (26% identical), SLC25A37 (24% identical), SLC25A48 (23% identical), SLC25A11 (22% identical), SLC25A20 (22% identical), SLC25A21 (22% identical), SLC25A28 (22% identical), SLC25A47 (22% identical), UCP3 (22% identical), and 37 more.
Diseases named in the same sentence as SLC25A26 in open-access papers:
SLC25A26 is named in the same sentence as 24 diseases in open-access papers, as found by Europe PMC text mining. Sharing a sentence is not in itself a finding about the gene and the disease. The quoted sentences say what the papers report.
cervical cancer (3 papers, 2020 to 2024). A primary or metastatic malignant neoplasm involving the cervix. "Indeed, several studies have shown that SAMC is downregulated in HCC and cervical cancer due to SLC25A26 gene promoter hypermethylation or the loss of the 3p12-p14 region." (PMID 39795950, 2024). "Recent studies have shown that SLC25A26 is abnormally expressed in some cancers, such as cervical cancer, low-grade glioma, non-small cell lung cancer, and liver cancer, which suggests SLC25A26 can affect the occurrence and development of some cancers." (PMID 38745827, 2024). "Relevant literatures reported that SLC25A26 showed low expression in both cervical cancer cells CaSki and HeLa25." (PMID 33041323, 2020). "In cervical cancer line CaSki and HeLa cells, SLC25A26 gene is also downregulated." (PMID 38745827, 2024).
breast carcinoma (2 papers, 2024 to 2025). "PLA2G6 and SLC25A26 have been identified as involved in the development of various tumors, though their link to breast cancer is still underexplored." (PMID 39720180, 2024).
liver cancer (2 papers, 2020 to 2024). An epithelial or non-epithelial malignant neoplasm that arises from the liver. "The experimental results of western blot, real-time PCR and immunohistochemistry all showed that SLC25A26 had low expression in liver cancer tissues compared to adjacent tissues." (PMID 33041323, 2020). "In human liver cancer tissues, SLC25A26 expression was low compared to adjacent tissues." (PMID 38745827, 2024). "We verified the expression of SLC25A26 in human clinical liver cancer tissues and adjacent tissues." (PMID 33041323, 2020). "In the human clinical liver cancer tissues with high expression of SLC25A26, proliferation index Ki67 had low expression and the senescence markers p16, p21, and HMGA1 had high expression, and the tissues with low expression of SLC25A26 had opposite effects." (PMID 38745827, 2024).
Respiratory insufficiency (2 papers, 2019 to 2022). "Patients with SLC25A26 mutations ranged from neonatal mortality resulting from respiratory insufficiency and hydrops to childhood acute episodes of cardiopulmonary failure and slowly progressive muscle weakness." (PMID 35464759, 2022).
glioblastoma (1 paper, 2024). The most malignant astrocytic tumor (WHO grade IV). "Expression of SLC25A26 in lower-grade glioma (GBMLGG) and glioblastoma (GBM), melanoma (SKCM), uveal melanoma (UVM), and colon and rectal cancer (COADREAD) has a significant negative correlation with the abundance of dendritic cells, M1 macrophages, and T helper 2 cells around them." (PMID 38745827, 2024).
hearing loss (1 paper, 2022). "Other genes were related to BPD-associated outcomes such as retinopathy of prematurity (ROP, e.g., GBP3, FJX1, HIPK2) and hearing loss (e.g., GJB6, TMEM63B) and mitochondrial energy metabolism (e.g., TOMM7, SLC25A26, SLC25A33, PDK1, PKM, MDH1)." (PMID 35484630, 2022).
hepatocellular carcinoma (1 paper, 2024). A malignant tumor that arises from hepatocytes. "A novel copper complex [Cu(ttpy-tpp)Br2]Br (Referred to as CTB) exerted an anti-hepatocellular carcinoma effect by up-regulating SLC25A26 expression level in mice." (PMID 38745827, 2024).
inflammatory bowel disease (1 paper, 2025). A spectrum of small and large bowel inflammatory diseases of unknown etiology. "Thirteen SNPs (e.g., EXOC3: 6, SLC25A26: 1, YIF1B: 6) and intestinal microbiomes were significant features of the random forest for the prediction of inflammatory bowel disease." (PMID 40941714, 2025).
non-small cell lung carcinoma (1 paper, 2024). A group of at least three distinct histological types of lung cancer, including non-small cell squamous cell carcinoma, adenocarcinoma, and large cell carcinoma. "In patients with non-small cell lung cancer, immune infiltration analysis showed that SLC25A26 expression was negatively correlated with 10-year survival." (PMID 38745827, 2024). "In non-small cell lung cancer, expression of SLC25A26 and the 10-year survival rate of the patients were negatively correlated." (PMID 38745827, 2024).
pulmonary hypertension (1 paper, 2022). Increased pressure within the pulmonary circulation due to lung or heart disorder. "Case 2 is a 4-month-old term male with compound heterozygous SLC25A26 mutation and severe pulmonary hypertension." (PMID 36533232, 2022).
cancer (4 papers, 2019 to 2024). A tumor composed of atypical neoplastic, often pleomorphic cells that invade other tissues. "Therefore, SLC25A26 abnormal expression or mSAMC dysfunction can be associated with multiple disease states, including cancer, nutrient deficiencies, and cardiovascular diseases." (PMID 38745827, 2024). "Therefore, we will briefly review mSAMC in different species and its encoding gene, focusing on the association of SLC25A26 gene aberrant expression and some cancers as well as potential mechanisms, and characteristics of mitochondrial diseases caused by SLC25A26 mutation." (PMID 38745827, 2024). "Studies from clinical trials, and animal and cell models indicate that SLC25A26 abnormal expression can regulate the occurrence and development of cancers." (PMID 38745827, 2024). "FOXD3 as an epigenetic regulator mediates the transcriptional repression of multiple cancer genes including SLC25A26 and NANOG." (PMID 36966276, 2023). "Growing studies showed that aberrant expression of SLC25A26 may be involved in the occurrence and development of some cancers." (PMID 38745827, 2024). "However, the relationship between SLC25A26 expression and the prognosis of other cancers as well as the specific predictive indicators remain to be investigated." (PMID 38745827, 2024). "In brief, these studies suggest that SLC25A26 expression level may be differently correlated with the prognosis in different cancers." (PMID 38745827, 2024). "Therefore, the occurrence and development of cancers can be controlled by regulating the expression of SLC25A26 to affect the activity of the methionine cycle metabolism." (PMID 38745827, 2024). "Altered SLC25A26 expression and its effects on some cancers." (PMID 38745827, 2024). "We speculate that SLC25A26 will be a potential new therapeutic target for some cancers." (PMID 38745827, 2024). "Therefore, upregulating SLC25A26 and limiting methionine intake in cancer cells may be able to further affect cellular methionine metabolism, potentially enhancing apoptosis and enhancing the effect of chemotherapy drugs." (PMID 38745827, 2024). "In addition, it should be explored whether SLC25A26 expression is relevant for predicting, detecting, or diagnosing certain cancers." (PMID 38745827, 2024). "Additionally, studies on CTB have shown that the suppression of extra-mitochondrial methylation by CTB-induced SLC25A26 overexpression can inhibit cancer cell genesis, progression, and proliferation by inhibiting the methylation of the telomerase reverse transcriptase promoter." (PMID 38745827, 2024). "Moreover, since DC, M1 macrophages, and Th2 have different mechanisms to directly or indirectly inhibit or kill cancer cells, increased SLC25A26 expression may promote the development of GBMLGG, SKCM, UVM, and COADREAD, whereas decreased SLC25A26 expression is beneficial to inhibit or kill them." (PMID 38745827, 2024). "No methylated sites were found in a CpG island in non-tumoral SLC25A26 promoter, while in CaSki and HeLa cancer cells, 13 and 15 methylated sites of DNA were found, respectively." (PMID 38745827, 2024).
mitochondrial disease (3 papers, 2022 to 2024). "Pathogenic, biallelic SLC25A26 variants are a recognized cause of mitochondrial disease in children, with a severe neonatal onset caused by decreased SAM transport activity." (PMID 35024855, 2022). "It has also been reported that SLC25A26 mutation may lead to mitochondrial defects and then induce a mitochondrial disease called combined oxidative phosphorylation deficiency 28 (COXPD28)." (PMID 38745827, 2024). "In conclusion, SLC25A26 mutations impair mitochondrial RNA stability, protein synthesis, LA, and CoQ10 biosynthesis, which further affect TCA and the mitochondrial oxidative respiratory chain, resulting in the intractable mitochondrial disease COXPD28." (PMID 38745827, 2024). "Furthermore, compared to the wild-type BCG group, the transcriptome of the B∆tbcm group showed downregulated genes, including SLC25A26 (− 3.276-fold), NDUFA8 (− 3.324-fold) and DTYMK (− 2.931-fold); the absence of these genes is associated with mitochondrial disease." (PMID 38110948, 2023).
tumor (3 papers, 2020 to 2025). "We obtained from the tumor growth curve that interfering with SLC25A26 significantly promoted tumor growth, which is consistent with our previous results." (PMID 33041323, 2020). "Altogether, these observations indicated that CTB exerts anti-tumor effect by regulating SLC25A26 in mice." (PMID 33041323, 2020). "The same results were also obtained in vivo, CTB inhibits the growth of subcutaneously implanted tumors in nude mice and promoted the expression of senescence markers in tumor tissues, and interference with SLC25A26 partially offset the antitumor effect of CTB." (PMID 33041323, 2020). "Next, we could see from the tumor growth curve that interfering with SLC25A26 significantly promoted tumor growth." (PMID 33041323, 2020). "Moreover, in a subcutaneous transplanted tumor model with MC38 cells, a mouse colon cancer cell lines, knockdown of SLC25A26 caused tumor volume to begin to decrease by day 9 and completely disappear by day 30, whereas control tumor volume continued to increase." (PMID 38745827, 2024). "Immuno-infiltration analysis also showed that SLC25A26 expression in several tumors has a positive or negative correlation with the abundance of immune cell subsets around the tumor tissue." (PMID 38745827, 2024). "Interestingly, the tumor tissues with low expression of SLC25A26 had high expression of proliferation index Ki67, while the senescence markers p16, p21, HMGA1 had low expression, and the tissue of high expression of SLC25A26 showed the opposite results." (PMID 33041323, 2020).
infection (1 paper, 2023). The state of being infected such as from the introduction of a foreign agent such as serum, vaccine, antigenic substance or organism. "Full complementation was observed for the expression levels of TRIM39, SARM1, SLC25A26, NDUFA8 and DTYMK by infection with C∆tbcm, which showed similar trends as wild-type BCG infection." (PMID 38110948, 2023).
myopathy (1 paper, 2022). A disease of the muscle in which the muscle fibers do not function properly. "We did, however, detect increased expression of solute carrier family 25A26 (SLC25A26), encoding the importer of S-adenosylmethionine, together with enhanced mtDNA copy numbers in myopathy fibroblasts compared to healthy controls." (PMID 35216315, 2022). "The enhanced SLC25A26 expression observed for myopathy skin fibroblasts does indicate an increase in mitochondrial SAM uptake compared to healthy fibroblasts." (PMID 35216315, 2022). "Intriguingly, levels of SLC25A26, a nuclear gene encoding the S-adenosylmethionine carrier (SAMC) localized in the mitochondrial inner membrane, were increased 2.7 ± 0.5-fold (p < 0.05) in myopathy patient fibroblasts compared to healthy control fibroblasts." (PMID 35216315, 2022).
SLC25A26 also shares sentences with these, for which no sentence is quoted: CODAS syndrome (1 paper); Depression (1); Down syndrome (1); glioma (1); hydrops (1); lactic acidosis (1); Mitochondrial myopathy (1); Ovarian Tumor (1); retinopathy of prematurity (1).